ECRG4 (ECRG4 augurin precursor)
Description:
Probable hormone that may attenuate cell proliferation and induce senescence of oligodendrocyte and neural precursor cells in the central nervous system (By similarity). ECRG4-induced senescence is characterized by G1 arrest, RB1 dephosphorylation and accelerated CCND1 and CCND3 proteasomal degradation (By similarity).
Synonyms: C2orf40; augurin
Tractability: Antibody: UniProt places it where antibodies can reach, with high confidence; UniProt predicts a signal peptide or a membrane-spanning region; its Gene Ontology location is reachable by antibodies, with medium confidence.
Gene: Protein-coding gene on chromosome 2 (106,063,246 to 106,078,155, forward strand). Ensembl gene ENSG00000119147.
Subcellular location: Secreted; Cytoplasm; Apical cell membrane
Gene Ontology:
Molecular function: protein binding
Biological process: anaphase-promoting complex-dependent catabolic process; cellular senescence; central nervous system development; G1 to G0 transition; regulation of cell population proliferation
Cellular component: apical plasma membrane; cytoplasm; extracellular region
Genetic constraint (gnomAD): Loss-of-function variants: 16 observed, 15.88 expected, observed/expected ratio (o/e) 1.01, 90% interval 0.68 to 1.52. The upper end of that interval is the gene's LOEUF score, 1.52, which puts it in group 6 of 6, group 1 being the genes least tolerant of losing a copy. Missense variants: 179 observed, 163.75 expected, observed/expected ratio (o/e) 1.09, 90% interval 0.97 to 1.24. Synonymous variants: 78 observed, 64.72 expected, observed/expected ratio (o/e) 1.21, 90% interval 1 to 1.46.
Homologues: Orthologues: chimpanzee C2AH2orf40 (99% identical), macaque ECRG4 (99% identical), rabbit ECRG4 (90% identical), dog ECRG4 (89% identical), guinea pig ECRG4 (84% identical), mouse Ecrg4 (84% identical), pig ECRG4 (80% identical), rat Ecrg4 (70% identical), tropical clawed frog ecrg4 (68% identical), zebrafish ecrg4a (48% identical), zebrafish ecrg4b (41% identical).
Diseases named in the same sentence as ECRG4 in open-access papers:
ECRG4 is named in the same sentence as 59 diseases in open-access papers, as found by Europe PMC text mining. Sharing a sentence is not in itself a finding about the gene and the disease. The quoted sentences say what the papers report.
esophageal cancer (13 papers, 2010 to 2023). A primary or metastatic malignant neoplasm involving the esophagus. "Recent studies have revealed that silencing of ECRG4 expression in colorectal carcinoma, kidney cancer, and esophageal cancer is associated with the hypermethylation of the ECRG4 promoter region." (PMID 30918105, 2019). "Furthermore, reduced ECRG4 expression in esophageal cancer patients is associated with an increased incidence of myocardial injury and atrial fibrillation." (PMID 36910669, 2023). "Previous studies demonstrate that ECRG4 is constitutively expressed in esophageal epithelial cells, and its degree of downregulation is directly proportional to prognosis in esophageal cancer patients." (PMID 36910669, 2023). "Downregulation of ECRG4 expression level correlates with esophageal cancer, as well as myocardial injuries and arrhythmias." (PMID 36910669, 2023). "Previous studies demonstrated that ECRG4 is constitutively expressed in esophageal epithelial cells, and its degree of downregulation is directly proportional to prognosis in patients with esophageal cancer." (PMID 36910669, 2023). "In a different study, the serum of patients with esophageal cancer contained high levels of esophageal cancer-related gene-4 (ECRG4) mRNA, a tumor suppressor gene that was found to inhibit tumor growth and angiogenesis." (PMID 33805398, 2021). "ECRG4/C2ORF40 is a potential tumor suppressor gene (TSG) recently identified in esophageal carcinoma." (PMID 22110708, 2011). "Another in vitro effect of ECRG4 overexpression is the inhibition of cell migration and invasion in cell lines from esophageal carcinoma and glioma." (PMID 22110708, 2011). "Notably, ECRG4 is also a tumor suppressor gene that can prevent esophageal cancer cell proliferation." (PMID 36910669, 2023). "Ecrg4 is a tumor suppressor potentially involved in esophageal cancer." (PMID 36092940, 2022). "We will then discuss how ECRG4 can be used in the treatment of tumors and arrhythmias, and provide a novel possible strategy to reduce the occurrence of perioperative cardiovascular adverse events in patients with tumors such as esophageal cancer and gastric cancer." (PMID 36910669, 2023). "ECRG4: Esophageal carcinoma-related gene 4 (ECRG4) is a novel candidate tumor suppressor gene that has frequently been found to be inactivated by promoter hypermethylation in different cancer types, including esophageal cancer, prostate cancer, gastric cancer, colorectal carcinoma, and glioma." (PMID 35327655, 2022).
glioma (12 papers, 2009 to 2025). A benign or malignant brain and spinal cord tumor that arises from glial cells (astrocytes, oligodendrocytes, ependymal cells). "The underlying mechanism of these observed effects was associated with the ability of ECRG4-EX to suppress the level of angiogenesis and inflammation-related factors in glioma cells." (PMID 37958619, 2023). "ECRG4 expression was associated with better survival in esophageal and prostate carcinomas, and with inhibition of cell proliferation and migration in esophageal cancer, colorectal cancer and glioma." (PMID 22110708, 2011). "However, the function and mechanisms mediated by the loss of ECRG4 expression in glioma remains unclear." (PMID 20598162, 2010). "ECRG4 inhibits the activity of NF-kB, suppressing the invasion, proliferation, and migration of glioma cells." (PMID 39857943, 2025). "In a recent study, exosomes derived from BMECs were used to inhibit the proliferation of gliomas by overexpressing a tumor suppressor gene, esophageal cancer-related gene-4 (ECRG4)." (PMID 37958619, 2023). "Subsequently, it was reported that ECRG4 was also involved in certain tumors, including colorectal carcinoma, prostate cancer, T-cell leukemia, gastric cancer and glioma." (PMID 23833667, 2013). "In esophagal, colo-rectal, and prostate carcinomas, and gliomas, promoter methylation is the main mechanism of ECRG4 silencing, and treatment with demethylating agents restore gene expression." (PMID 22110708, 2011). "To study the biological functions of ECRG4, we introduced ECRG4 into U251 glioma cells using a pEGFP-N1 eucaryotic expression vector containing ECRG4 gene." (PMID 20598162, 2010). "We demonstrated the functional importance of ECRG4 in suppression of glioma cell growth, migration, and invasion." (PMID 20598162, 2010). "We became interested in ECRG4 because it is normally expressed in the brain yet was found to be downregulated in gliomas." (PMID 20598162, 2010). "We found that restoration of ECRG4 expression in glioma U251 cells inhibited expression of transcription factor NF-κB." (PMID 20598162, 2010). "Of the 10 paired samples analyzed, 9 glioma tissues displayed the decreased expression of ECRG4 compared to matched normal brain tissues." (PMID 20598162, 2010). "Our study has revealed a novel function of ECRG4 in suppression of glioma cell migration and invasion, implicating its potential involvement in cancer metastasis." (PMID 20598162, 2010). "In conclusion, we found that the ECRG4's role as a tumor suppressor was supported by our observation that its expression is decreased in glioma." (PMID 20598162, 2010). "In order to assess the role of ECRG4 in glioma, we performed real-time PCR to measure the expression of ECRG4 mRNA transcripts in 10 paired gliomas and their adjacent brain tissues." (PMID 20598162, 2010). "In order to assess the role of ECRG4 in glioma, we first performed real-time PCR to measure the expression of ECRG4 mRNA transcripts in 10 paired gliomas and their adjacent brain tissues." (PMID 20598162, 2010). "We were further interested in exploring the molecular mechanism of ECRG4 tumor-suppression in glioma." (PMID 20598162, 2010). "The effect of ECRG4 expression on cell proliferation, invasion, and migration was investigated in human U251 glioma cells." (PMID 20598162, 2010). "In this study, we examined the mRNA expression of ECRG4 and investigated its biological role in glioma cells." (PMID 20598162, 2010). "ECRG4 has been shown to be a candidate tumor suppressor in several tumors, but its role in glioma remains poorly understood." (PMID 20598162, 2010).
glioma (continued). "In the present study, we examined the expression of ECRG4 in gliomas and explored its role as a tumor-suppressor gene in glioma cells in vitro." (PMID 20598162, 2010). "Furthermore, we applied gain-of-function approach to examine the biological processes regulated by ECRG4 in glioma cells." (PMID 20598162, 2010). "Based on their finding, we speculated ECRG4 might also be involved in glioma cell growth suppression by regulating the NF- B pathway." (PMID 20598162, 2010). "However, further investigation is necessary to determine the exact role of ECRG4 in the NF-κB pathway within the context of glioma." (PMID 20598162, 2010). "The results from a colony formation assay showed that ECRG4-overexpressing ECRG4-5 and -7 cells formed significantly less colonies than Control clone cells (P < 0.001 for both cell types), suggesting an inhibitory effect of ECRG4 on anchorage-dependent growth of glioma cells." (PMID 20598162, 2010). "Consistent with this hypothesis, we showed that overexpression of ECRG4 in glioma U251 cells markedly downregulated expression of NF-κB by western blot." (PMID 20598162, 2010). "Real-time PCR was used to examine expression of ECRG4 in gliomas and their matched brain tissues." (PMID 20598162, 2010). "To examine whether ECRG4 plays a suppressive role in glioma pathogenesis, we applied a gain-of-function approach by introducing ECRG4 into cells to investigate its biological function." (PMID 20598162, 2010). "The observation that ECRG4 regulates multiple cellular processes such as cell growth, cell cycle, migration, and invasion in multiple cancers implies it is an important therapeutic target for multiple human cancers, including glioma." (PMID 20598162, 2010). "Our data suggest that ECRG4 serves as a tumor suppressor in glioma." (PMID 20598162, 2010). "We provided a preliminary molecular mechanism of ECRG4-mediated suppression of glioma cell growth." (PMID 20598162, 2010). "Next, we analyzed 71 glioma samples for methylation of the ECRG4 promoter by COBRA." (PMID 20017917, 2009). "Finally, we found that overexpression of ECRG4 could inhibit expression of NF-kB which may provide a mechanism explaining ECRG4's role in controlling glioma cell proliferation." (PMID 20598162, 2010). "This suggested that ECRG4 may be involved in NF-κB pathway in glioma." (PMID 20598162, 2010). "Chromosome 2 open reading frame 40 (C2orf40), also known as esophageal cancer‐related gene 4 (ECRG4), a tumor suppressor, is hypermethylated in cancers such as colorectal carcinoma, glioma, breast cancer, gastric cancer, and bladder cancer." (PMID 39957375, 2025). "To this end, we chose the U251 glioma cell line which exhibits relatively low expression level of endogenous ECRG4 (data not shown) and provides a biologically relevant model for our study." (PMID 20598162, 2010).
breast carcinoma (10 papers, 2009 to 2025). "We observed that human breast cancer samples showed reduced ECRG4 expression, and this was associated with hypermethylation of the ECRG4 promoter." (PMID 30918105, 2019). "While the specific mechanisms of low expression of ECRG4 in breast cancer samples were unclear, we then explored the association of ECRG4 promoter methylation with ECRG4 expression." (PMID 30918105, 2019). "Moreover, further exploration of ECRG4 methylation profiling as an early diagnostic tumor marker or an indicator of the pathogenesis and prognosis of breast cancer is warranted." (PMID 30918105, 2019). "Several studies have shown that the ECRG4 promoter is frequently hypermethylated in patients with breast cancer, gastric cancer, and nasopharyngeal carcinoma, resulting in the downregulation of ECRG4." (PMID 32922434, 2020). "Given the reduction in cell viability, we next assessed how ECRG4 overexpression influences breast cancer apoptosis." (PMID 30918105, 2019). "Collectively, we found that ECRG4 expression is reduced in human breast cancer samples, possibly as a result of the hypermethylation of the ECRG4 promoter region." (PMID 30918105, 2019). "Collectively, our findings indicate that ECRG4-induced apoptosis in breast cancer likely results from the activation of the mitochondrial apoptotic pathway." (PMID 30918105, 2019). "We next analyzed the effect of ECRG4 overexpression on cell cycle progression in breast cancer cell lines by flow cytometry." (PMID 30918105, 2019). "To that end, we assessed the link between ECRG4 expression and DNA methylation in cell lines as well as in breast cancer samples, thus probing the potential epigenetic regulation of ECRG4." (PMID 30918105, 2019). "Our study validated that ECRG4 promoter hypermethylation is a potentially important mechanism governing ECRG4 down-regulation in breast cancer." (PMID 30918105, 2019). "ECRG4 is silenced in human breast cancer cells and cell lines, likely owing to promoter hypermethylation." (PMID 30918105, 2019). "ECRG4 overexpression impaired breast cancer cell proliferation and migration, and led to G0/G1 cell cycle phase arrest." (PMID 30918105, 2019). "Last, we validated that ECRG4 overexpression induces apoptosis, possibly via activation of the mitochondrial apoptotic pathway in these breast cancer cell lines." (PMID 30918105, 2019). "In the MCF-7 and BT483 breast cancer cell lines we also found that ECRG4 inhibits cell growth and migration, and that ECRG4 overexpression induces apoptosis, possibly via mitochondrial apoptotic pathway activation." (PMID 30918105, 2019). "Herein, we assess the correlation between ECRG4 expression and DNA methylation, probing the potential epigenetic regulation of ECRG4 in breast cancer." (PMID 30918105, 2019). "We found that human breast cancer samples exhibited increased methylation of the ECRG4 promoter and decreased ECRG4 expression." (PMID 30918105, 2019). "Although recent studies have strongly suggested that ECRG4 is a potential potent TSG that suppresses breast cancer development, its precise role in this disease remains to be fully explored." (PMID 30918105, 2019). "Meta-analysis of histo-clinical correlations in our series of more than 1.000 cases further reinforced the idea that ECRG4 is a candidate TSG in breast cancer." (PMID 22110708, 2011). "Through the analysis of more than 350 breast cancers, we show that ECRG4 is underexpressed in 94% of tumors." (PMID 22110708, 2011). "The tumor suppressor function of ECRG4 and the cellular consequences of its silencing remain to be investigated in breast cancer." (PMID 22110708, 2011). "Here, we have analyzed the expression of ECRG4 in a large series of breast cancers profiled using DNA microarrays and its correlation with histo-clinical features and survival." (PMID 22110708, 2011).
breast carcinoma (continued). "ECRG4 may thus be a pivotal factor in the pathogenesis of breast cancer, and therefore represents a potentially attractive target for therapeutic intervention." (PMID 30918105, 2019). "However, additional research in primary breast cancer samples is needed in order to better understand the link between ECRG4 expression and its promoter methylation status." (PMID 30918105, 2019). "ECRG4 acts as a TSG in breast cancer, and may induce apoptosis via the mitochondrial apoptotic pathway and block the cell cycle at the G0/G1 phase by regulating the Cyclin–CDK–CKI network." (PMID 30918105, 2019). "Moreover, ECRG4 induced the formation of the Cytc/Apaf-1/caspase-9 apoptosome and promoted breast cancer cell apoptosis." (PMID 30918105, 2019). "Our study shows that ECRG4 promotes apoptosis in breast cancer cell lines." (PMID 30918105, 2019). "Whatever the mechanism of silencing, restoring ECRG4 expression in the tumor, either by epigenetic therapy or application of recombinant protein, may represent a promising novel therapeutic approach in breast cancer." (PMID 22110708, 2011). "However, this is a single example, which calls for methylation analysis of more cancer cell lines and tissue samples since it is likely that promoter methylation contributes for silencing ECRG4 in breast cancer." (PMID 22110708, 2011). "Based on our observations and literature data, we speculate that ECRG4 underexpression confers growth and migration advantages to breast cancers, leading to poor prognosis." (PMID 22110708, 2011). "Our results suggest that ECRG4 is a candidate TSG in breast cancer." (PMID 22110708, 2011). "Finally, we assessed the correlation between ECRG4 expression and the response to neo-adjuvant chemotherapy in early breast cancer." (PMID 22110708, 2011). "Our data suggest that ECRG4 is a candidate TSG in breast cancer, the expression of which may help improve the prognostication." (PMID 22110708, 2011). "In conclusion, we report the first large-scale analysis of ECRG4 expression in breast cancer." (PMID 22110708, 2011). "To elucidate the role of ECRG4 hypermethylation in human tumor cells, we analyzed the methylation of its promoter in eleven cancer cell lines from colorectal, lung, cervix, hepatocellular and breast carcinoma, fibrosarcoma and glioblastoma." (PMID 20017917, 2009). "This suggests that ECRG4 may inhibit breast cancer proliferation and migration." (PMID 30918105, 2019). "Therefore, the hypermethylation of ECRG4 promoter may contribute to the down-regulation of ECRG4 mRNA levels in breast cancer." (PMID 30918105, 2019). "We found that overexpression of ECRG4 in MCF-7 and BT483 breast cancer cells inhibit cell growth and migration." (PMID 30918105, 2019). "We analyzed ECRG4 promoter methylation via methylation-specific PCR (MSPCR), bisulfite sequencing, and a promoter reporter assay in human breast cancer cell lines and samples." (PMID 30918105, 2019). "Furthermore, we observed that ECRG4 expression was positively correlated with OGN, which is a tumor suppressor in colorectal cancer and breast cancer." (PMID 32922434, 2020). "We validated that ECRG4 may serve as a potential TSG in breast cancer, and further explored the exact role of ECRG4 in breast cancer cells." (PMID 30918105, 2019). "We first quantified the mRNA expression level of endogenous ECRG4 by qPCR assay in 17 donor tissues, comparing expression in pairs of breast cancer tissues and matched non-tumor tissues." (PMID 30918105, 2019). "Although esophageal cancer-related gene 4 (ECRG4) is thought to be a possible potent tumor suppressor gene that acts to suppress breast cancer, its precise role in this disease is not understood." (PMID 30918105, 2019). "Of note, all breast cancer cell lines profiled in our laboratory also showed very low expression of ECRG4 when compared to HME1, a non-tumorigenic mammary cell line derived from mammoplasty (data not shown)." (PMID 22110708, 2011).
breast carcinoma (continued). "Moreover, ECRG4 may increase p21 expression to enhance the inhibition of cyclinE–CDK2 and cyclinA–CDK2 in breast cancer." (PMID 30918105, 2019). "Surprisingly, no data are available regarding ECRG4 expression in breast cancer." (PMID 22110708, 2011). "We found that the breast cancer samples had a higher frequency of ECRG4 promoter methylation than paired non-tumor tissues, and promoter region methylation status had a negative correlation with ECRG4 mRNA expression level, which was consistent with previous study." (PMID 30918105, 2019).